EIF3C (eukaryotic translation initiation factor 3 subunit C)
Description:
Component of the eukaryotic translation initiation factor 3 (eIF-3) complex, which is required for several steps in the initiation of protein synthesis. The eIF-3 complex associates with the 40S ribosome and facilitates the recruitment of eIF-1, eIF-1A, eIF-2:GTP:methionyl-tRNAi and eIF-5 to form the 43S pre-initiation complex (43S PIC). The eIF-3 complex stimulates mRNA recruitment to the 43S PIC and scanning of the mRNA for AUG recognition. The eIF-3 complex is also required for disassembly and recycling of post-termination ribosomal complexes and subsequently prevents premature joining of the 40S and 60S ribosomal subunits prior to initiation. The eIF-3 complex specifically targets and initiates translation of a subset of mRNAs involved in cell proliferation, including cell cycling, differentiation and apoptosis, and uses different modes of RNA stem-loop binding to exert either translational activation or repression.
Synonyms: EIF3S8; eIF3-p110
Tractability: Small molecule: a structure with a bound ligand is known. PROTAC: ubiquitination databases record sites on it; its protein half-life has been measured.
Gene: Protein-coding gene on chromosome 16 (28,688,558 to 28,735,730, forward strand). Ensembl gene ENSG00000184110.
Subcellular location: Cytoplasm
Subcellular location (Human Protein Atlas): Cytosol
Pathways (Reactome):
Metabolism of proteins: Formation of a pool of free 40S subunits; Formation of the ternary complex, and subsequently, the 43S complex; GTP hydrolysis and joining of the 60S ribosomal subunit; L13a-mediated translational silencing of Ceruloplasmin expression; Ribosomal scanning and start codon recognition; Translation initiation complex formation
Gene Ontology:
Molecular function: protein binding; ribosome binding; RNA binding; translation initiation factor activity; translation initiation factor binding
Biological process: positive regulation of translation; translational initiation; formation of cytoplasmic translation initiation complex; cytoplasmic translational initiation
Cellular component: cytosol; eukaryotic translation initiation factor 3 complex; cytoplasm; eukaryotic 43S preinitiation complex; eukaryotic 48S preinitiation complex
Genetic constraint (gnomAD): Loss-of-function variants: 2 observed, 8.44 expected, observed/expected ratio (o/e) 0.24, 90% interval 0.096 to 0.75. That is too few expected variants to judge how well the gene tolerates losing a copy. Missense variants: 16 observed, 79.01 expected, observed/expected ratio (o/e) 0.2, 90% interval 0.14 to 0.31. Synonymous variants: 2 observed, 23.4 expected, observed/expected ratio (o/e) 0.0855, 90% interval 0.034 to 0.27.
Homologues: Orthologues: macaque EIF3C (99% identical), rabbit EIF3C (99% identical), guinea pig EIF3C (98% identical), mouse Eif3c (97% identical), rat Eif3c (96% identical), tropical clawed frog eif3c (81% identical), zebrafish eif3c (77% identical), Drosophila melanogaster eIF3c (52% identical), Caenorhabditis elegans eif-3.C (43% identical). Paralogues in human: EIF3CL (100% identical).
Diseases named in the same sentence as EIF3C in open-access papers:
EIF3C is named in the same sentence as 35 diseases in open-access papers, as found by Europe PMC text mining. Sharing a sentence is not in itself a finding about the gene and the disease. The quoted sentences say what the papers report.
ovarian carcinoma (41 papers, 2019 to 2025). A malignant neoplasm originating from the surface ovarian epithelium. "In the present study, to explore the molecular pathways potentially linked to ovarian cancer, changes in gene expression in eIF3c-downregulated SKOV3 human ovarian cancer cells were investigated using GeneChip microarray and pathway analysis." (PMID 31316002, 2019). "The YTHDF1/EIF3C axis is involved in the invasion process in ovarian cancer; EIF3H participates in the invasion of hepatocellular carcinoma and the EIF4A3/FLOT1 pathway promotes invasion and tumor proliferation in lung adenocarcinoma." (PMID 40705973, 2025). "YTHDF1 enhances EIF3C translation in an m6A‐dependent manner by binding to m6A‐modified EIF3C mRNA, thereby promoting tumorigenesis and metastasis in ovarian cancer." (PMID 39006762, 2024). "YTHDF1 enhances EIF3C translation in an m6A-dependent manner by binding to m6A-modified EIF3C mRNA, thereby promoting overall translational output and facilitating ovarian cancer tumorigenesis and metastasis." (PMID 38724996, 2024). "eIF3C was also involved in the regulation of a variety of human cancers, such as ovarian cancer, lung adenocarcinoma, and renal cell carcinoma." (PMID 38274829, 2023). "Mechanistically, YTHDF1 promotes the translation of EIF3C by binding to m6A-modified EIF3C mRNA and concomitantly determines the overall translational output, thereby facilitating tumorigenesis and metastasis of ovarian cancer." (PMID 36650570, 2023). "And through multi-omics studies, it is determined that its direct target in ovarian cancer cells is the translation initiation factor EIF3C, and YTHDF1 controls the translation of EIF3C in a m6A-dependent manner." (PMID 37005667, 2023). "Previous studies had revealed that EIF3C was inevitable for tumor progression in many cancer types, including lung cancer, glioma, and ovarian cancer." (PMID 35650605, 2022). "EIF3C was extensively reported involved in the progression of lung cancer, glioma, breast cancer, and ovarian cancer." (PMID 35650605, 2022). "YTHDF1 promoted the eIF3C translation in ovarian cancer, thus promoting the development and metastasis of ovarian cancer." (PMID 35197112, 2022). "It was reported that m6A reader YTHDF1 bound to m6A-modified EIF3C mRNA and promoted the translation of EIF3C and the overall translational output, consequently facilitating tumorigenesis and metastasis of ovarian cancer." (PMID 36249071, 2022). "YTHDF1 promotes ovarian cancer tumorigenesis and metastasis by binding to m6A-modified eIF3c mRNA and enhancing eIF3c translation in a m6A-dependent manner while promoting overall translational output." (PMID 36360287, 2022). "The m6A reader YTHDF1 was proved to promote ovarian cancer progression via augmenting EIF3C translation." (PMID 36072430, 2022). "Eukaryotic Translation Initiation Factor 3 Subunit C (EIF3C) exerts its oncogenic function by promoting its translation in an m6A-dependent manner that lead to tumor growth and metastasis in ovarian cancer." (PMID 33692959, 2021). "Recently, it was found that YTHDF1 regulates the translation of eIF3C via an m6A-dependent way, thus affects the global protein translation in OC, enhancing protein synthesis and promoting the tumorigenesis of ovarian cancer cells." (PMID 34794452, 2021). "For example, YTHDF1 promoted the translation of eIF3C by binding to m6A-modified eIF3C mRNA and increased the general translational output, so as to facilitating tumorigenesis of ovarian cancer." (PMID 34345203, 2021). "YTHDF1 accelerated the growth and metastasis of ovarian cancer in vivo and in vitro by promoting the m6A-modified translation of EIF3C." (PMID 34497675, 2021). "YTHDF1, an m6A Reader, was found to augment EIF3C translation by binding to m6A-modified EIF3C mRNA and to further promote tumorigenesis and metastasis in ovarian cancer." (PMID 32549786, 2020).
ovarian carcinoma (continued). "There is evidence that the m6A reader YTHDF1 can enhance the translation of EIF3C and its expression, promoting the malignant progression of ovarian cancer." (PMID 32449290, 2020). "In the present study, we detected differences in gene expression, biological processes, proliferation and apoptosis in the human ovarian cancer cell line SKOV3 after silencing of eIF3c." (PMID 31316002, 2019). "Eukaryotic initiation factor 3c (EIF3c) plays an important role in protein translation and cancer cell growth and proliferation, but its role in human ovarian cancer is unclear." (PMID 31316002, 2019). "In conclusion, these results indicate that by dysregulating translational initiation, eIF3c plays an important role in the proliferation and survival of human ovarian cancer cells." (PMID 31316002, 2019). "It is reasonable to deduce that eIF3c, which regulates translation initiation, plays an important role in the proliferation and survival of human ovarian cancer cells." (PMID 31316002, 2019). "As an oncogene, YTHDF1 can affect the overall protein translation in ovarian cancer cells by promoting the translation and overall output of protein translation initiation factor EIF3C mRNA, thus promoting the proliferation, migration, and invasion of ovarian cancer cells." (PMID 38343637, 2024). "The m6A reader YTHDF1 promoted ovarian cancer progression via augmenting EIF3C translation." (PMID 38714753, 2024). "Moreover, YTHDF1 can directly target EIF3C and augment EIF3C translation in an m6A-dependent manner, facilitating the tumorigenesis and metastasis of ovarian cancer." (PMID 33758623, 2021). "A recent study using multi-omics analysis reported that YTHDF1 promotes ovarian cancer occurrence and development through binding to m6A-modified EIF3C mRNA and consequently enhancing the EIF3C translation, which EIF3C is a subunit of the protein translation initiation factor EIF335." (PMID 32934298, 2020). "The present study investigated the expression and function of eIF3c in ovarian cancer." (PMID 31316002, 2019). "Therefore, we analysed differential gene expression by GeneChip microarray, the functions and networks of differentially expressed genes by IPA, and cell proliferation and apoptosis after silencing of eIF3c in the SKVO3 ovarian cancer cell line." (PMID 31316002, 2019). "However, little is known about the role of eIF3c in human ovarian cancer." (PMID 31316002, 2019). "The mammalian homolog YTHDF1 stimulates translation directly and indirectly via stimulation of eIF3C translation, and amplification of YTHDF1 stimulates proliferation in ovarian cancer." (PMID 41322074, 2025). "In the realm of ovarian cancer, YTH domain-containing family protein 1 (YTHDF1) is known to enhance the translation of eukaryotic translation initiation factor 3 subunit C, thereby driving tumorigenesis and metastasis." (PMID 38255219, 2024). "Studies have shown that YTHDF1 can promote the proliferation and metastasis of ovarian cancer cells by binding to the m6A-modified EIF3C gene and increasing the translation of eukaryotic translation initiation factor 3 subunit C (EIF3C)." (PMID 39468015, 2024). "For instance, in ovarian cancer cells, the upregulation of m6A reader YTHDF1 specifically binds m6A-modified Eukaryotic Translation Initiation Factor 3 Subunit C (EIF3C) mRNA and facilitates its translation." (PMID 36750826, 2023). "In ovarian cancer, YTHDF1 promotes the translation of eukaryotic translation initiation factor 3 subunit C (EIF3C), a component of the protein translation initiation factor EIF3 complex." (PMID 37086786, 2023). "Then the increased EIF3C, a subunit of the protein translation initiation factor EIF3, can promote ovarian cancer tumorigenesis and metastasis." (PMID 36750826, 2023). "In ovarian cancer, YTH domain-containing family protein 1 (YTHDF1) promotes the translation of eukaryotic translation initiation factor 3 subunit C to promote tumorigenesis and metastasis." (PMID 36581942, 2022).
ovarian carcinoma (continued). "Some scholars have proposed that YTHDF1 directly targets eIF3C (a subunit of EIF3) and promotes ovarian cancer’s occurrence, metastasis, and prognosis." (PMID 35707365, 2022). "In ovarian cancer, YTHDF1 facilitates tumorigenesis and metastasis by promoting the translation of EIF3C mRNA in an m6A-dependent manner." (PMID 35806168, 2022). "For instance, YTHDF1 can increase the translation of Eukaryotic translation initiation factor 3 subunit C (ELF3C) and promote the overall translation output by combining with the m6A-modified ELF3C mRNA, thus promoting the occurrence and metastasis of ovarian cancer." (PMID 33692959, 2021). "In ovarian cancer, YTHDF1 could bind to EIF3C mRNA with m6A modification to elevate translation of EIF3C, thereby leading to tumorigenesis and metastasis." (PMID 34116604, 2021). "YTHDF1 augmented the translation of EIF3C (HGNC:3279) in an m6A-dependent manner by binding to m6A-modified EIF3C mRNA and concomitantly promoted the overall translational output, thereby facilitating tumorigenesis and metastasis of ovarian cancer." (PMID 35087827, 2021). "YTHDF1 binds with m6A-modified EIF3C (a subunit of protein translation initiation factor EIF3) mRNA to enhance EIF3C translation, and at the same time promotes the overall translation output, thereby promoting the ovarian cancer occurrence and transfer." (PMID 33552994, 2020). "EIF3C is the direct target of YTHDF1, and increased overall translational output of EIF3C by the regulation of YTHDF1 may facilitate the tumorigenesis and metastasis of ovarian cancer." (PMID 36051357, 2022). "However, there is currently little to no research regarding the role of eIF3c in ovarian cancer." (PMID 31316002, 2019).
hepatocellular carcinoma (8 papers, 2018 to 2025). A malignant tumor that arises from hepatocytes. "EIF3C promotes proliferation, migration and invasion of prostate, ovarian and hepatocellular carcinoma cells and was associated with resistance to erlotinib in lung cancer." (PMID 32183388, 2020). "Increased expression of EIF3C, both in cells and exosomes, has previously been shown to promote the development and progression of hepatocellular carcinoma by improving cell proliferation and angiogenesis." (PMID 35743538, 2022). "Upregulation of eukaryotic translation initiation factor 3 subunit C (EIF3C) in human hepatocellular carcinoma cells increased the secretion of proangiogenic small EVs." (PMID 35887332, 2022). "In hepatocellular carcinoma (HCC), high expression of eIF3C is associated with poor survival." (PMID 30925917, 2019). "In human hepatocellular carcinoma, EIF3C activated expression of S100A11 involved in EIF3C-exosome increased tube formation in angiogenesis." (PMID 37864150, 2023).
lung carcinoma (7 papers, 2015 to 2022). "To provide additional support for this model, we sought to determine the relevance of lung carcinoma-associated single base pair mutations identified in eIF3b and eIF3c genes." (PMID 26172298, 2015). "To this end, we used the Catalogue of somatic mutations in cancer (COSMIC) library to derive two - yet uncharacterized - single base pair somatic mutations in eIF3b and eIF3c that have been confirmed in lung carcinoma." (PMID 26172298, 2015). "Two lung cancer-associated mutations in eIF3b and eIF3c that have been tested in course of this study also had the capacity to reverse the reduced size phenotype, indicating that both mutations do not represent loss-of-function mutants of the eIF3-complex." (PMID 26172298, 2015). "This study was designed to explore the role and mechanism of EIF3C in lung cancer proliferation and apoptosis to provide new therapeutic biomarkers for predicting the progression of this disease." (PMID 36157221, 2022). "In vivo experiments using a transplanted tumor nude-mouse model suggested that EIF3C promoted lung cancer tumorigenesis." (PMID 36157221, 2022). "Several studies have already reported the harmful effect of high expression of EIF3 subunits in lung cancer, including EIF3C, EIF3D, and EIF3H." (PMID 36051357, 2022). "Flow cytometry assay indicated that low EIF3C expression enhanced the apoptosis of lung cancer cells (p < 0.001)." (PMID 36157221, 2022). "This study was designed to explore the role and mechanism of eukaryotic initiation factor 3C (EIF3C) in the proliferation and apoptosis of lung cancer cells." (PMID 36157221, 2022). "In vivo experiments using transplanted tumor nude-mouse model suggested that EIF3C promoted lung cancer tumorigenesis." (PMID 36157221, 2022). "A transplanted tumor nude-mouse model was established to clarify the role of EIF3C in lung cancer in vivo." (PMID 36157221, 2022). "Silencing EIF3C suppressed the proliferation and promoted the apoptosis of lung cancer cells." (PMID 36157221, 2022). "In summary, we suggested for the first time that EIF3C is upregulated in lung cancer tissues and may enhance the proliferation and suppress the apoptosis of lung cancer cells by regulating the APP/HSPA1A/LMNB1 axis." (PMID 36157221, 2022). "A transplanted tumor nude-mouse model was established to clarify the role of EIF3C in lung cancer." (PMID 36157221, 2022). "EIF3C expression in clinic lung cancer tissues was detected by immunohistochemistry assay." (PMID 36157221, 2022). "EIF3C was abnormally overexpressed in lung cancer cell lines and tissues." (PMID 36157221, 2022). "In the present study, EIF3C was found to be abnormally overexpressed in lung cancer tissues." (PMID 36157221, 2022). "In our study, we first demonstrated that EIF3C was overexpressed in lung cancer." (PMID 36157221, 2022). "EIF3C overexpression may facilitate the proliferation and hamper the apoptosis of lung cancer cells by regulating the APP/HSPA1A/LMNB1 axis." (PMID 36157221, 2022). "Nevertheless, whether EIF3C promotes lung cancer tumorigenesis by regulating HSPA1A via the PI3K/AKT pathway warrants further investigation." (PMID 36157221, 2022). "Silencing EIF3C hampered the proliferation and promoted the apoptosis of lung cancer cells." (PMID 36157221, 2022). "EIF3C expression in clinic lung cancer tissues was detected using immunohistochemistry." (PMID 36157221, 2022). "All of these findings suggested that EIF3C is abnormally expressed in lung cancer tissues and might play a significant function in lung tumorigenesis." (PMID 36157221, 2022). "ZNF280A may promote the development of lung adenocarcinoma by interacting with EIF3C, thus implying that EIF3C may have a potential role in lung cancer." (PMID 36157221, 2022).
lung carcinoma (continued). "Here, using a newly-established erlotinib-resistant cell line, PC9/ER, from PC9 lung cancer cells, we demonstrated that the expression of translation-related molecules, including eukaryotic translation initiation factor 3 subunit C (eIF3c), was upregulated in PC9/ER cells by proteome analyses." (PMID 30680067, 2018). "EIF3C may serve as a novel therapeutic biomarker in lung cancer." (PMID 36157221, 2022). "In addition, EIF3C could facilitate the proliferation and inhibit the apoptosis of lung cancer cells and promote the tumorigenesis of lung cancer." (PMID 36157221, 2022). "Thus, we speculated that EIF3C may play a carcinogenic role in lung cancer by regulating LMNB1." (PMID 36157221, 2022). "Thus, we speculated that EIF3C may promote lung cancer tumorigenesis by regulating APP." (PMID 36157221, 2022). "Studies that further validated the interaction between EIF3C and the predicted genes, especially their regulatory effect on lung cancer progression, are lacking." (PMID 36157221, 2022). "However, the role and specific regulatory mechanism of EIF3C in lung cancer tumorigenesis have not been fully studied." (PMID 36157221, 2022). "However, the significance of EIF3C and its potential correlated genes in the prognosis and disease development of lung cancer has not been revealed in the present study and would be the future direction of our investigations." (PMID 36157221, 2022).